CMTM1 (CKLF like MARVEL transmembrane domain containing 1)
Synonyms: CKLFSF1; CKLFH1a; CKLFH; CKLFH1
Tractability: Antibody: UniProt predicts a signal peptide or a membrane-spanning region.
Gene: Protein-coding gene on chromosome 16 (66,566,393 to 66,579,137, forward strand). Ensembl gene ENSG00000089505.
Subcellular location: Membrane
Subcellular location (Human Protein Atlas): Nucleoplasm
Gene Ontology:
Cellular component: membrane
Genetic constraint (gnomAD): Loss-of-function variants: 9 observed, 15.14 expected, observed/expected ratio (o/e) 0.59, 90% interval 0.36 to 1.04. The upper end of that interval is the gene's LOEUF score, 1.04, which puts it in group 4 of 6, group 1 being the genes least tolerant of losing a copy. Missense variants: 348 observed, 388.78 expected, observed/expected ratio (o/e) 0.9, 90% interval 0.82 to 0.98. Synonymous variants: 168 observed, 161.97 expected, observed/expected ratio (o/e) 1.04, 90% interval 0.91 to 1.18.
Homologues: Orthologues: chimpanzee CMTM1 (99% identical), macaque CMTM1 (62% identical), dog CMTM1 (47% identical), mouse Cmtm1 (31% identical), rat Cmtm1 (30% identical), Caenorhabditis elegans F28H1.4 (9% identical), Caenorhabditis elegans F47B3.3 (5% identical). Paralogues in human: CKLF (21% identical), CMTM2 (15% identical), CMTM3 (13% identical), PLP2 (12% identical), CMTM4 (10% identical), CMTM5 (10% identical), CMTM7 (9% identical), PLLP (9% identical), CMTM8 (8% identical), CMTM6 (8% identical), MALL (7% identical), MAL (7% identical), and 2 more.
Diseases named in the same sentence as CMTM1 in open-access papers:
CMTM1 is named in the same sentence as 21 diseases in open-access papers, as found by Europe PMC text mining. Sharing a sentence is not in itself a finding about the gene and the disease. The quoted sentences say what the papers report.
breast cancer (6 papers, 2019 to 2025). A primary or metastatic malignant neoplasm involving the breast. "For example, the isoform of CMTM1-v17 is highly expressed in many human tumors such as breast cancer and hepatocellular carcinoma (HCC)." (PMID 40179060, 2025). "An In vitro study in a breast cancer cell line found that CMTM1 eliminated TNF-α-induced apoptosis and eventually promoted breast cancer cell proliferation." (PMID 35252165, 2022). "Previous studies have found that CMTM1 is closely related to the occurrence, development, and treatment of breast cancer and lung cancer, but studies on the occurrence and development of CMTM1 in HCC have not been reported." (PMID 33585698, 2021). "In MDA-MB-231 breast cancer cell lines, overexpression of CMTM1 can promote the proliferation of breast cancer cells and resist apoptosis induced by tumor necrosis factor-α (TNF-α)." (PMID 33585698, 2021). "In breast cancer tissues, the mRNA expression levels of only CMTM1, CMTM5, CMTM6, and CMTM7 were measured." (PMID 31998718, 2019). "CMTM1-v17 prevents TNF-α-induced apoptosis by activating the NF-kB pathway and promoting cellular proliferation in breast cancer." (PMID 40179060, 2025). "The mRNA expression levels of CMTM5 and CMTM7 were significantly downregulated while those of CMTM1 and CMTM6 were significantly upregulated in breast cancer tissues than in corresponding normal tissues." (PMID 31998718, 2019). "CKLF Like Marvel Transmembrane Domain Containing 1 (CMTM1) plays a role in breast cancer and lung cancer, but studies on the occurrence and development of CMTM1 in hepatocellular carcinoma (HCC) have not been reported." (PMID 33585698, 2021).
glioblastoma (5 papers, 2019 to 2024). The most malignant astrocytic tumor (WHO grade IV). "Another study investigated the overexpression of CMTM genes on glioblastoma cell proliferation and invasion and revealed that CMTM1 and 3 promote tumor invasion, and their expression was significantly correlated with shorter overall survival." (PMID 38223763, 2024). "Research reported that high expression of CMTM1 in glioblastoma enhanced aggressive tumor behavior, resulting in a worse prognosis." (PMID 36975415, 2023). "CMTM1 was upregulated in glioblastoma and CMTM1 overexpression enhanced aggressive tumor behavior, which was associated with worse overall survival in glioblastoma patients." (PMID 36975415, 2023). "High expression of CMTM1 is significantly related to the shorter overall survival of patients with glioblastoma, suggesting that CMTM1 is a priority target for glioblastoma." (PMID 33585698, 2021). "CMTM1 overexpression in the glioblastoma cell line A172 also promotes the proliferation and migration of tumor cells, which is likely to be achieved by the activation of epidermal growth factor receptor (EGFR), Src family kinase, and Wnt signaling." (PMID 31754330, 2019). "In fact a previous study even indicated that higher CMTM1 and CMTM3 expression levels are significantly associated with shorter overall survival in glioblastoma." (PMID 31998718, 2019). "Besides, CMTM1 also promotes the invasion and proliferation of glioblastoma cells." (PMID 33585698, 2021). "However, the specific mechanism of CMTM1 in the development of glioblastoma is unclear." (PMID 31754330, 2019). "Consequently, the study showed that CMTM1 and CMTM3 can be targets for treating glioblastoma." (PMID 38223763, 2024).
hepatocellular carcinoma (3 papers, 2021 to 2025). A malignant tumor that arises from hepatocytes. "Survival analyses showed that CMTM1 could be an independent post hoc factor in hepatocellular carcinoma." (PMID 38223763, 2024).
lymphoma (3 papers, 2020 to 2021). A malignant (clonal) proliferation of B- lymphocytes or T- lymphocytes which involves the lymph nodes, bone marrow and/or extranodal sites. "CMTM1 is overexpressed in lymphoma cells, and the addition of CMTM1 polypeptide in vitro can induce apoptosis of lymphoma cells." (PMID 33585698, 2021). "A new study found that CMTM1-v5 specifically induced the human lymphoma cells apoptosis and may be a novel therapeutic for lymphoma treatment." (PMID 33282744, 2020).
autoimmune disease (2 papers, 2020 to 2021). A disorder resulting from loss of function or tissue destruction of an organ or multiple organs, arising from humoral or cellular immune responses of the individual to their own tissue constituents. "In the study of autoimmune diseases, it has been found that CMTM1 may be involved in the occurrence and development of arthritis by interacting with the C–C chemokine receptor 4 (CCR4)." (PMID 33585698, 2021).
lung carcinoma (2 papers, 2021 to 2022). "The CMTM1 gene has also been reported by two independent studies to be associated with lung cancer at transcriptomics and methylation levels, respectively." (PMID 35155435, 2022).
glioma (1 paper, 2022). A benign or malignant brain and spinal cord tumor that arises from glial cells (astrocytes, oligodendrocytes, ependymal cells). "In this study, we found that the expression of CMTM1 was higher in grade III glioma in the TCGA datasets." (PMID 35252165, 2022). "Results showed that the expression level of CMTM1, CMTM3, CMTM6, CMTM7, CMTM8, and CKLF was elevated in high-grade gliomas (grade III; p < 0.01)." (PMID 35252165, 2022).
kidney cancer (1 paper, 2021). Primary or metastatic malignant neoplasm involving the kidney. "Additional examples among the core CT genes are CMTM1 (signaling molecule) and SLC1A6 (amino acid transporter), which are unfavorable expression markers for pancreatic and urothelial cancer, while KHDRBS3 (RNA splicing) and GLUD2 (glutamate dehydrogenase) are favorable markers for kidney cancer." (PMID 33426787, 2021).
liver cancer (1 paper, 2020). An epithelial or non-epithelial malignant neoplasm that arises from the liver. "the expression level of CMTM1-v17 mRNA was high in liver cancer." (PMID 33282744, 2020).
ovarian carcinoma (1 paper, 2022). A malignant neoplasm originating from the surface ovarian epithelium. "Importantly, in the current study, we showed evidence of an association between CMTM1/3/5/8 and the overall survival of ovarian cancer patients." (PMID 36110202, 2022). "This study showed that CMTM family members such as CMTM1/2/3/6/8 had abnormal expression in ovarian cancer and could cause poor prognosis." (PMID 36110202, 2022). "RT-qPCR showed that CMTM1/6/8 was highly expressed in ovarian cancer cell lines." (PMID 36110202, 2022). "The expression level of multiple members of CMTMs, such as CMTM1/2/3/6, was closely related to the level of immune cell infiltration and multiple immune checkpoints and may lead to the poor prognosis of ovarian cancer through related immunological mechanisms." (PMID 36110202, 2022). "Interestingly, we found that CMTM1/6/8 was aberrantly highly expressed in ovarian cancer cell lines, which is highly consistent with the results of the previous database analysis of this study." (PMID 36110202, 2022). "Among them, especially for ovarian cancer, CMTM3/4/6/7/8 had a relatively high expression in ovarian cancer compared to control normal tissues, while CMTM1/2/5 had a relatively low expression." (PMID 36110202, 2022). "The analysis of the immune microenvironment in this study showed that the expression level of CMTM1/2/3/6 had a certain correlation with the infiltration of a variety of immune cells (B cells, macrophages, neutrophils, dendritic cells, and CD4+ cells) in ovarian cancer." (PMID 36110202, 2022). "Also, CMTM1/2/3/6 had a certain correlation with the changes in the immune microenvironment such as immune cell infiltration and immune checkpoint expression, which may be the potential mechanism of the CMTM family in ovarian cancer." (PMID 36110202, 2022).
prostate carcinoma (1 paper, 2021). A carcinoma that arises from epithelial cells of the prostate gland. "CMTM1-v17, an RNA splicing form of CMTM1, is highly expressed in both normal prostate tissues and prostate cancer-originated cell lines." (PMID 33585698, 2021).
rheumatic diseases (1 paper, 2021). "In addition, CMTM1 is associated with the occurrence of rheumatic diseases." (PMID 33585698, 2021).
Sepsis (1 paper, 2024). Sepsis is defined as life-threatening organ dysfunction caused by a dysregulated host response to infection. "Our comprehensive bioinformatics analysis revealed that CMTM1-6 are upregulated in sepsis, with CMTM3 showing differential expression between survival and non-survival groups, suggesting a distinct role for CMTM3 in sepsis progression." (PMID 39455728, 2024).
cancer (11 papers, 2015 to 2026). A tumor composed of atypical neoplastic, often pleomorphic cells that invade other tissues. "CMTM4 is tightly linked with CMTM1-3 on chromosome 16q22.1, a genomic region prone to both genetic and epigenetic modifications in various cancers." (PMID 26474560, 2015). "Moreover, CMTM1 is recently found to be associated with the development, progression, and metastasis of various malignant tumors." (PMID 33585698, 2021). "CMTM1 consists of 23 isoforms, of which the CMTM1-v17 protein is up-regulated in expression in various cancers." (PMID 38223763, 2024). "Univariate Cox analysis revealed that the expression of CMTM1, CMTM4, CMTM7, and cancer stage were significantly associated with poor prognosis in patients with HCC (p < 0.05)." (PMID 36975415, 2023). "The CKLF-like MARVEL transmembrane domain-containing (CMTM) family regulates aggressive phenotype in many cancers, which consists of 8 member proteins (CMTM1-8)." (PMID 35429970, 2022). "This review highlights new findings regarding the roles of CMTM1–8 in cancer, particularly in tumor growth, metastasis, and immune evasion." (PMID 32944388, 2020). "Previous studies showed that the expression of CMTM1 increased significantly in various cancer samples, suggesting that CMTM1 may play a vital role in tumorigenesis." (PMID 35252165, 2022). "CMTM family (CMTM1-8) has been reported to be differentially expressed between tumor and normal tissue, thus suggesting that CMTMs may actively regulate tumor development in various cancer types 15-17." (PMID 34475993, 2021). "The mRNA expression of CKLF, CMTM1, CMTM3, CMTM4, and CMTM7 was correlated with the cancer stage, revealing that patients with more advanced cancer stages tended to have higher mRNA expression of the CMTM family." (PMID 36975415, 2023). "The core CT genes include CMTM1, CT83 (CXorf61), EZHIP (CXorf67), DCAF4L2, KHDRBS3, LEMD1, PIWIL1, and SPATA6, which contribute to cancer progression and metastasis." (PMID 33426787, 2021). "The expression of CKLF, CMTM1, CMTM3, and CMTM7 was correlated with cancer stage and tumor grade." (PMID 36975415, 2023). "CMTM1–8 are known tumor suppressor genes; in addition, CMTM6 is a key regulator of PD-L1 in various human cancer cells." (PMID 31998718, 2019).
tumor (11 papers, 2015 to 2025). "Chemokine-like factor (CKLF)-like MARVEL transmembrane domain-containing 1 (CMTM1) was upregulated in testis and many tumor tissues, and also raised cell proliferation rates and resistance to tumor necrosis factor-α (TNF-α)-induced apoptosis." (PMID 34408975, 2021). "It is a new androgen receptor co-inhibitor and exerts its tumor suppressor function by recruiting histone deacetylases, indicating that the CMTM1 gene is a potential tumor suppressor gene." (PMID 33585698, 2021). "CMTM4 is the most conserved member of this family and forms a gene cluster with CKLF and CMTM1-3 on chromosome 16q22.1, a locus that is frequently deleted or modified in multiple tumours and that harbours a number of tumour suppressor genes." (PMID 26474560, 2015). "Furthermore, overexpression of CMTM1 in the glioma cell line A172 promotes tumor cell proliferation and migration, possibly through activation of epidermal growth factor receptor (EGFR), SRC kinase, and WNT signaling pathways." (PMID 38223763, 2024). "According to the available studies, CMTM1 is highly expressed in testicular and tumor tissues, suggesting that CMTM1 might play a vital role in tumorigenesis." (PMID 33585698, 2021). "Combined with the results of PCR and bioinformatics analysis, we speculate that CMTM1 may serve as a potential tumor promoting role in HCC progression." (PMID 33282744, 2020). "When analyzing chemotherapy efficacy in the correlation of the expression level of CMTM1_v17, patients with low CMTM1_v17 expression in the tumor tissues after NAC suggested higher PR rates than those with high CMTM1_v17 expression, which were confirmed in 78 NSCLC patients who have received NAC." (PMID 28129775, 2017). "We first conducted IHC to detect the protein expression of CMTM1 in HCC and paired adjacent non-tumor tissues." (PMID 33585698, 2021). "The positive expression of CMTM1 in HCC and adjacent non-tumor tissues were 84% (63/75) and 89.3% (67/75), respectively, indicating a high expression of CMTM1 both in HCC and adjacent non-tumor tissues (P = 0.079)." (PMID 33585698, 2021). "In this study, the expression of CMTM1 in HCC and adjacent non-tumor tissues was detected by immunohistochemistry (IHC) method." (PMID 33585698, 2021). "As tumor grade increased, the mRNA expression of CKLF, CMTM1, CMTM3, and CMTM7 tended to be higher." (PMID 36975415, 2023). "The CMTM1–4 genes form a gene cluster on chromosome 16, whereas CMTM6–8 form the second gene cluster on chromosome 3p22.3, where many critical tumor suppressor genes are located." (PMID 32944388, 2020). "IHC detection indicated that CMTM1 protein was highly expressed in both HCC and adjacent non-tumor tissues, with a positive expression in 84% (63/75) of HCC tissues and 89.3% (67/75) of adjacent non-tumor tissues." (PMID 33585698, 2021). "When the tumor tissues without recurrence/metastasis was compared with SACC-LM and tumor tissues with recurrence/metastasis, the result showed that CMTM1 might have enhanced the effectively of anti-tumor metastasis in SACC." (PMID 33282744, 2020). "However, we didn’t find a different protein expression of CMTM1 between HCC and paired adjacent non-tumor tissues from IHC results, which may be due to different tumor sources, different malignant degrees, or different detection methods." (PMID 33585698, 2021).
CMTM1 also shares sentences with these, for which no sentence is quoted: Arthritis (1 paper); benign tumors (1); liver cirrhosis (1); papillary adenoma (1); small cell lung carcinoma (1); tubular adenoma (1).